EGFR (epidermal growth factor receptor)
Diseases named in the same sentence as EGFR in open-access papers (continued):
Sharing a sentence is not in itself a finding about the gene and the disease.
head and neck tumors (continued). "It is estimated that 33-50% of epidermal tumors present overexpression of EGFR, being observed in more than 90% of head and neck tumors." (PMID 23207070, 2012). "In 2006, the FDA approved the use of cetuximab, a chimeric anti-EGFR mAb, for the treatment of patients with head and neck tumors presenting overexpression of this protein." (PMID 23207070, 2012). "Epidermal growth factor receptor overexpression is known to be associated with advanced TNM stage, higher histologic grade, and recurrent head and neck tumours." (PMID 18268492, 2008). "Clinical benefit has been demonstrated in patients with head and neck tumours receiving an anti-epidermal growth factor receptor (EGFR) agent in combination with radiotherapy (RT)." (PMID 18577994, 2008). "Epidermal growth factor receptor levels ranged from 388 to 33794 fmol mg−1 protein, a range that is similar to that found in head and neck tumours." (PMID 11986789, 2002). "Notably, EGFR is one of the most critical oncogenic drivers in head and neck tumors, with several targeted therapies already in clinical use." (PMID 40904507, 2025). "Given the overexpression of EGFR in more than 90% of head and neck tumors and the poorer survival of these patients, it was hypothesized that patients would benefit greatly from the use of anti-EGFR drugs." (PMID 36982894, 2023). "Multiple clinical trials led by Rosenthal and colleagues have successfully demonstrated the use of Cetuximab and Panitumumab (anti-EGFR monoclonal antibodies) conjugated to IRDye800CW for surgical resection of head and neck tumors, 95% of which overexpress EGFR." (PMID 35837101, 2022). "ELF3 is highly expressed in head and neck tumors and upregulates the epidermal growth factor receptor (EGFR) and human epidermal growth factor receptor 2 (HER2) to attenuate the antiproliferative effects of EGFR/HER2 tyrosine kinase inhibitors (lapatinib and afatinib)." (PMID 35845594, 2022). "Although there is no direct evidence of genetic alteration in the Wnt pathway in head and neck tumors, several works demonstrated that this pathway might be over-induced as a results of trans activation of EGFR and PI3K signaling." (PMID 34572265, 2021). "They reported 42-80% high expression of EGFR in head and neck tumor tissues." (PMID 33273921, 2020). "Therefore, this study focused on the expression levels of EGFR in head and neck tumors with data evaluated for its significance in disease progression." (PMID 33273921, 2020). "Epidermal growth factor receptor (EGFR) has been found to be highly expressed in breast and other tumors; therefore, there is the need to investigate the level of EGFR expression among patients with head and neck tumors in Ghana." (PMID 33273921, 2020). "For HNSCC, epidermal growth factor receptor (EGFR) has been identified as a suitable candidate and various exploratory preclinical and clinical trials have indicated the potential of this concept in aiding surgeons during head and neck tumor removal." (PMID 32516897, 2020). "Interestingly, EGFR is a widely studied oncogene in head and neck tumors and agents targeting EGFR have emerged as a potential adjuvant therapy for OSCC." (PMID 24495306, 2014). "Indeed, the functional crosstalk between GPCRs and EGFR contributes to the progression of colon, lung, breast, ovarian, prostate and head and neck tumors." (PMID 23144692, 2012). "In addition to protein overexpression, around 10-17% of the head and neck tumors present EGFR gene amplification, as shown by FISH analysis." (PMID 23207070, 2012). "Hence, EGFR can be used as a therapeutic target for the treatment of head and neck tumors." (PMID 33273921, 2020). "Investigations were performed using a VEGF-secreting human head and neck tumour cell line, CAL33, with a high EGFR content, injected as orthotopic xenografts into the mouth floor of nude mice." (PMID 18577994, 2008).
head and neck tumors (continued). "Given that EGFR-TKI therapy confers a survival benefit in some patients with colon, pancreatic, or head and neck tumors that are WT for EGFR, the amount of activated EGFR may be an important marker for the response to TKI therapy in such tumors." (PMID 29069773, 2017). "Taken together, these results suggest that heterodimerization of EGFR with IGF-1R can lead to increased activity of EGFR and may be an important platform for cetuximab mediated signaling in head and neck tumors that have become resistant to anti-EGFR therapy." (PMID 27716204, 2016). "The main reason is that the mechanism of EGFR-TKI is not well understood, and the role of abnormal EGFR signaling in head and neck tumor development remains unclear." (PMID 24602316, 2014). "EGFR antibodies improve progression-free survival in head and neck tumors but not overall survival." (PMID 39408603, 2024). "EGFR-targeted photodynamic therapy (PDT) could successfully kill head and neck tumor organoids and does not affect organoids of normal tissue formation due to low EGFR expression level in the latter." (PMID 37427120, 2023). "Epidermal growth factor receptor (EGFR) is overexpressed in head and neck cell lines, ionizing radiation induces translocation of EGFR into the nucleus and leads to activation of PI3K and RAS pathway, which supports proliferation and survival of head and neck tumor cells." (PMID 33885910, 2021). "Unlike observations in head and neck tumors, HPV-negative patients had higher EGFR amplification while HPV-positive patients exhibited lower EGFR amplification." (PMID 41516122, 2025).
neurodegenerative disease (44 papers, 2013 to 2025). A disorder of the central nervous system characterized by gradual and progressive loss of neural tissue and neurologic function. "Intriguingly, we identified EGFR as a major hub module (ranked by degree), interacting with numerous neurodegenerative disease risk genes." (PMID 41001519, 2025). "EGFR plays an important role in oligodendrogliogenesis and myelin production and is associated with the onset of neurodegenerative diseases such as AD, PD, and ALS." (PMID 39273172, 2024). "Under normal conditions, in the absence of injury or pathology, astrocytes exist as quiescent astrocytes with barely detectable levels of EGFR, but loss of normal astrocyte function is known to be associated with the pathology of neurodegenerative diseases." (PMID 36672736, 2023). "EGFR is a transmembrane protein and pro-activation of EGFR is one of the most common pathogenic driver events under various inflammatory conditions, including neurodegenerative diseases such as AD." (PMID 36712676, 2022). "Epidermal growth factor receptor (EGFR) is a tyrosine kinase receptor involved in cell differentiation and proliferation, and its mutation and amplification are associated with the pathology of neurodegenerative diseases." (PMID 36237735, 2022). "Thus, EGFR could be a useful target for treating neuroinflammation-associated neurodegenerative diseases." (PMID 36341365, 2022). "EGFR has been shown to play a role in regeneration and maintenance of the CNS and also in the onset neurodegenerative diseases." (PMID 38438772, 2024). "Activated EGFR has been proposed in the pathophysiology of neurodegenerative diseases and neuroinflammation." (PMID 33368549, 2021). "Afatinib, an orally available EGFR tyrosine kinase inhibitor, inhibits EGFR activation to alleviate neuroinflammation by reducing caspase 1 activation and interleukin-1β levels in neurodegenerative diseases." (PMID 32231518, 2020). "Importantly, alterations of EGFR trafficking and signaling are associated with the onset and progression of several neurodegenerative diseases suggesting that modulation of EGFR expression or signaling could be useful to stimulate regeneration or counteract neurodegeneration." (PMID 32806510, 2020). "Receptor tyrosine kinases such as EGFR/ErbB and RET are involved in numerous neuronal functions and altered pathways associated with the development of neurodegenerative diseases." (PMID 32967368, 2020). "Pathologically, EGFR has been proposed to be involved in several neurodegenerative diseases, including Alzheimer’s disease, spinal cord injury and brain ischemia." (PMID 30792526, 2019). "Activated epidermal growth factor receptor (EGFR) has been proposed in the pathophysiology of neurodegenerative diseases." (PMID 30792526, 2019). "Along with our previous study showing that afatinib inhibited OGD-induced neuroinflammation in astrocytes, it appears that EGFR-TKIs may be a novel repurposing drug for CNS neurodegenerative diseases, including ICH." (PMID 40444141, 2025). "Accordingly, a pathological role of EGFR signaling is suggested in CNS neurodegenerative diseases." (PMID 40444141, 2025). "EGFR activation by metals has been supposed to be involved in some neurodegenerative diseases." (PMID 34501555, 2021). "Several lines of evidence suggested that the EGFR signaling pathway could play a role in the pathophysiology of many neurodegenerative diseases, including ALS." (PMID 28236105, 2017). "However, EGFR is expressed in both the central and peripheral nervous systems, and its trafficking and signaling are known to be involved in the onset and progression of neurodegenerative diseases and acute ischemic brain injury." (PMID 39537601, 2024). "The fact that EGFR inhibitors could be helpful in the treatment of AD seems to be in contrast with the role of this receptor in neurodegenerative disease since in PD and in other studies regarding AD, EGFR-altered signaling could contribute to neurodegeneration." (PMID 32806510, 2020).
neurodegenerative disease (continued). "Furthermore, EGFR-TKIs may be promising in inhibiting neuroinflammation in the CNS neurodegenerative diseases." (PMID 30792526, 2019). "Therefore, EGFR-TKIs, such as afatinib may possess an anti-inflammatory activity against neuroinflammation in the CNS neurodegenerative diseases." (PMID 30792526, 2019). "Therefore, it will be interesting to see how the two forms of CDC42 affect the expression and/or activation levels of mTOR and the EGFR in adult brains and whether the deregulation of these CDC42 splice variants is involved in the pathogenesis responsible for neurodegenerative diseases." (PMID 36206843, 2022).
cardiovascular diseases (37 papers, 2013 to 2025). "EGFR, also known as the ErbB1 receptor, exerts complex effects on various cellular behaviors associated with cardiovascular diseases." (PMID 40552149, 2025). "The risk of cardiotoxicity associated with EGFR-TKIs is particularly linked to patients’ cardiovascular history, and elderly individuals are more susceptible to cardiovascular diseases." (PMID 40552149, 2025). "EGFR transactivation plays a key role in Ang II-induced VSMC inflammation associated with cardiovascular diseases." (PMID 30046277, 2018). "Activation of the RAAS has been associated to activation of EGFR signalling in renal and cardiovascular diseases." (PMID 26064952, 2015). "In addition, it was reported that EGFR gene is a marker of pleiotropic effects in underlying kidney function and cardiovascular disease." (PMID 36009032, 2022). "EGFR, which is the most characterized member, contributes to cardiovascular disorders by causing an increase in oxidative stress, macrophage infiltration, release of proinflammatory cytokines, and transformation of SMC phenotype by a mechanism referred to as “transactivation”." (PMID 32160892, 2020). "Activation of EGFR has been implicated in many cardiovascular diseases." (PMID 29360846, 2018). "Epidermal growth factor (EGF) is an important epithelial-derived mediator that signals through EGF receptor (EGFR) and has been implicated in numerous disease such as cancer, cardiovascular disease, chronic renal disease, diabetes and allergic diseases such as asthma." (PMID 28855674, 2017). "EGFR was significantly lower in patients diagnosed with cardiovascular disease (p = 0.004) and higher MELD score (p < 0.001) in this analysis." (PMID 39772140, 2024). "EGFR transactivation appears as a critical actor in cardiovascular disease pathophysiology, and in vivo and in vitro evidence concerning the role of the crosstalk of EGFR with TP and AT1R in these processes has been piling up." (PMID 35741065, 2022). "The established paradigm can be expanded to reveal EGFR behaviors under other disease conditions, such as autoimmune, neurodegenerative, and cardiovascular diseases." (PMID 35955894, 2022). "To find a correlation between MR, EGFR and cardiovascular disorders, we explore the effect of changes in EGFR expression on cardiovascular gene expression." (PMID 34168192, 2021). "This indicates that a subgroup of the population is especially prone to changes in EGFR expression and possibly also to MR-mediated cardiovascular diseases." (PMID 34168192, 2021). "Oxidative stress is well characterized in cardiovascular disease, and ROS trans-activates EGFR through HB-EGF production." (PMID 28427241, 2017). "Epidermal growth factor receptor (EGFR) has been found to play a role in the pathogenesis of various cardiovascular diseases." (PMID 26762600, 2016). "Based on the role of EGFR and its ligands in cardiovascular disease, EGFR inhibitors should be explored as a therapeutic strategy." (PMID 24132149, 2013). "While it is clear that EGFR activity is essential for normal cardiac development, its function in the vasculature and its role in cardiovascular disease are only beginning to be elucidated." (PMID 24132149, 2013). "In this review, we focus on the reported activity of EGFR and its ligands in cardiovascular disease." (PMID 24132149, 2013). "The role of Amphiregulin/EGFR in cardiovascular diseases has been reported." (PMID 35732465, 2022). "Therefore, there may be a crosstalk between estrogen and S1P in COX-2 expression modulating different cellular functions mediated through MMP/EGFR/MAPKs in various cardiovascular diseases." (PMID 35242277, 2022). "The NF-kB signaling pathway is also observed with molecules EGFR, INSR, RAF1 and IGF1R involved in the pathway, this pathway is involved in cardiovascular disease and angiogenesis." (PMID 37569355, 2023).
cardiovascular diseases (continued). "While inhibition of EGFR may produce adverse cardiovascular effects, they are generally manageable and do not necessarily preclude consideration of EGFR inhibitors for the treatment of cardiovascular disorders." (PMID 24132149, 2013).
gastrointestinal tumors (36 papers, 2001 to 2025). "Taken together, our data shapes our understanding of epitope-changing EGFR mutations in gastrointestinal tumors showing that two different mutations can arise early on during EGFR-targeted treatment." (PMID 26059438, 2015). "EGFR transactivation may also be important in NE gastrointestinal tumours in which IGFR is commonly expressed and has been implicated in growth control." (PMID 14583782, 2003). "A recent study found that macrophages marked with phosphorylated EGFR play a crucial role in the development of the inflammation-mediated stages of colon carcinogenesis." (PMID 36146640, 2022). "Several studies have demonstrated that patients with digestive tumors benefited from EGFR-targeted therapy using cetuximab." (PMID 35903247, 2022). "Cetuximab (Cet), a US Food and Drug Administration- (FDA-) approved mAb, is widely used for treating digestive tumors with high EGFR expression." (PMID 35903247, 2022). "The integration of endoscopy with near infrared fluorescence imaging and photothermal therapy was aided by the accumulation of our multifunctionalized PEG-GNR-Cy5.5-anti-EGFR-antibody gold nanorods within gastrointestinal tumor xenografts in BALB/c mice." (PMID 30899637, 2019). "During treatment of a variety of solid tumours, particularly digestive system tumours, carriers modified by Anti-EGFR have shown obvious synergistic attenuation and antitumour effects." (PMID 28729631, 2017). "Our data demonstrate that the inhibition of EGFR-TK by gefitinib induces growth inhibition, apoptosis and cell-cycle arrest in NE gastrointestinal tumour cells." (PMID 14583782, 2003). "In the present study, we provide evidence that NE gastrointestinal tumour cells express both EGFR and the EGFR transactivating IGFR-β1." (PMID 14583782, 2003). "To conclude, our study provides evidence that the EGFR-TK inhibitor gefitinib induces both cell-cycle arrest and apoptosis in NE gastrointestinal tumour cells." (PMID 14583782, 2003). "Moreover, gefitinib, a specific EGFR-TK inhibitor, was found to inhibit potently the growth of NE gastrointestinal tumour cells by inducing cell-cycle arrest and/or apoptosis." (PMID 14583782, 2003). "Hence, in the present study, we examined the antineoplastic potency of the selective EGFR-TK inhibitor gefitinib in a set of NE gastrointestinal tumour cell lines with different growth characteristics." (PMID 14583782, 2003). "Combination anti-VEGF and anti-EGFR therapy may represent a novel therapeutic strategy for the management of colon peritoneal carcinomatosis." (PMID 11506500, 2001). "EGFR signaling is coupled directly or via adaptor proteins to MAPK signaling, PI3/AKT pathway, which plays a crucial role in DMH/AOM-induced colon carcinogenesis, JAK/STAT (Janus kinase/signal transducer and activator of transcription) pathways." (PMID 26504896, 2015).